SHBG (sex hormone binding globulin)
Diseases named in the same sentence as SHBG in open-access papers (continued):
Sharing a sentence is not in itself a finding about the gene and the disease.
autism (continued). "Although significant differences by autism status were identified in concentrations of sex hormone binding globulin overall and of estradiol in participant subgroups, differences by PNMS exposure failed to reach statistical significance, which may reflect insufficient statistical power." (PMID 37573326, 2023). "Early second trimester maternal steroid-related serum biomarkers (i.e., estradiol, free testosterone, total testosterone, and sex hormone binding globulin) were compared between pregnancies corresponding to offspring with (N = 68) and without (N = 68) autism." (PMID 37573326, 2023). "Interestingly, the current study found lower SHBG levels in the autism cohorts with and without PNMS exposure." (PMID 37573326, 2023).
autoimmune disease (2 papers, 2023 to 2024). A disorder resulting from loss of function or tissue destruction of an organ or multiple organs, arising from humoral or cellular immune responses of the individual to their own tissue constituents. "In the context of autoimmune diseases, elevated SHBG may worsen RA outcomes by reducing free testosterone, which is known to exert anti-inflammatory effects." (PMID 39759528, 2024).
cardioembolic stroke (2 papers, 2021 to 2025). "When evaluating the role of SHBG in disease, MR analysis suggests that an increase in SHBG contributes to a decrease in risk of cardioembolic stroke." (PMID 34226637, 2021).
central precocious puberty (2 papers, 2016 to 2023). "In conclusion, baseline LH and SHBG can serve as relevant indicators for determining rapidly progressive central precocious puberty." (PMID 38317710, 2023). "This study aimed to investigate the diagnostic value of luteinizing hormone (LH) basal values and sex hormone-binding globulin (SHBG) for rapidly progressive central precocious puberty (RP-CPP)." (PMID 38317710, 2023). "Detection of basal LH and SHBG levels allows for early diagnosis of the progression of central precocious puberty." (PMID 38317710, 2023). "This study calculated ROC curves and found that when SHBG levels were ≤58.79 nmol/L, the sensitivity and specificity for diagnosing RP-CPP were 67.5% and 74.1%, respectively, indicating that SHBG has some predictive value for the progression of central precocious puberty." (PMID 38317710, 2023).
congenital adrenal hyperplasia (2 papers, 2024 to 2025). Congenital adrenal hyperplasia (CAH) is an inherited endocrine disorder caused by a steroidogenic enzyme deficiency that is characterized by adrenal insufficiency and variable degrees of hyper or hypo androgyny manifestations, depending of the type and the severity of the disease. "Androgen concentrations and SHBG levels (nmol/L) of nine untreated 46,XX congenital adrenal hyperplasia patients with a male sex of rearing." (PMID 39175568, 2024).
coronary atherosclerosis (2 papers, 2018 to 2024). Atherosclerosis of the coronary vasculature. "Interestingly, delta-BMI is also inversely associated with sex hormone-binding globulin (SHBG), which aligns with previous studies showing an inverse relationship between SHBG and adiposity, coronary atherosclerosis, and cardiometabolic disease." (PMID 38918595, 2024).
deep vein thrombosis (2 papers, 2023 to 2025). "The goal of the present study was to explore the causal roles of endogenous sex hormones, including hormone-binding globulin (SHBG), bioactive testosterone (BT), and total testosterone (TT), in VTE and its two subgroups, deep vein thrombosis (DVT) and pulmonary embolism (PE)." (PMID 37880771, 2023).
dilated cardiomyopathy (2 papers, 2021 to 2024). Cardiomyopathy which is characterized by dilation and contractile dysfunction of the left and right ventricles. "An interesting study in patients with dilated cardiomyopathy demonstrated that cardiomyocytes express an androgen-binding protein, similar to SHBG, and the subcellular distribution matched with androgen receptor location." (PMID 34335746, 2021). "Recent studies discovered SHBG in the human heart produced by cardiomyocytes in dilated cardiomyopathy patients, indicating that SHBG transports sex steroids into the heart and may have a direct effect on heart condition." (PMID 38660513, 2024).
hepatitis C (2 papers, 2016 to 2025). "We relied on free T measurement using equilibrium dialysis, given the high prevalence of hepatitis C and HIV in our cohort and the SHBG abnormalities associated with these chronic infections." (PMID 41140716, 2025).
hypoalbuminaemia (2 papers, 2021). "Although information in SHBG is lacking in foals, hypoalbuminemia is a frequent finding, especially in septic foals." (PMID 33277956, 2021).
idiopathic osteoporosis (2 papers, 2015 to 2025). "A recent meta-analysis identified that an increase in SHBG may contribute to idiopathic osteoporosis, further corroborating our findings." (PMID 40078581, 2025). "SHBG correlated negatively with BMD at the femoral neck, both in idiopathic osteoporosis (r=-0.34, p <0.01) and secondary osteoporosis (r=-0.34, p < 0.01)." (PMID 31105806, 2015).
inflammatory bowel disease (2 papers, 2024 to 2025). A spectrum of small and large bowel inflammatory diseases of unknown etiology. "We conducted a Mendelian randomization (MR) analysis to investigate the relationship between female sex hormone levels (SHBG, total testosterone, bioavailable testosterone, and estradiol) and inflammatory bowel disease (IBD)." (PMID 39944207, 2025). "We conducted a Mendelian randomization (MR) analysis to examine the relationship between male sex hormone levels (SHBG, total testosterone, bioavailable testosterone, and estradiol) and inflammatory bowel disease (IBD)." (PMID 39944207, 2025).
kidney stone (2 papers, 2022 to 2023). "The inverse association between SHBG and kidney impairment was observed and in line with a previous MR study, and we further noticed that high SHBG might prevent or delay kidney stone formations." (PMID 35218343, 2022). "An observational study found that sex hormones (including testosterone, dihydrotestosterone, estradiol, and SHBG were significantly different in kidney stone formers in comparison to the healthy population, which may help explain the higher incidence in males than in females." (PMID 37624788, 2023).
lung carcinoma (2 papers, 2016 to 2021). "Ovarian sex steroid hormones have been suggested to counteract lung cancer development, and sex hormone‐binding globulin (SHBG) is essential in sex hormones regulation." (PMID 33595913, 2021).
malignant neoplasm of uterus (2 papers, 2022 to 2025). "In uterine cancer, excess fat increases estrogen production and lowers sex hormone-binding globulin (SHBG), leading to endometrial overgrowth and higher cancer risk." (PMID 41189943, 2025).
metabolic dysfunction-associated steatohepatitis (2 papers, 2023 to 2026). Metabolic dysfunction-associated steatohepatitis (MASH, formerly known as nonalcoholic steatohepatitis or NASH) is a type of fatty liver disease. "Circulating sex hormone-binding globulin (SHBG) concentrations are lower in individuals with metabolic dysfunction-associated steatotic liver disease (MASLD) and metabolic dysfunction-associated steatohepatitis (MASH), reflecting its potential role in metabolic liver dysfunction." (PMID 42278422, 2026).
metastatic disease (2 papers, 2015 to 2019). "Four BD proteins, including PZ, AZGP1, SHBG, and VWF, were selected for further testing by ELISA using a cohort of 52 PDAC patients, including 19 stage III and 33 stage IV with metastatic disease." (PMID 31346328, 2019).
nasopharyngeal carcinoma (2 papers, 2018 to 2025). A carcinoma arising from the nasopharyngeal epithelium. "In this study, SHBG was identified for the first time as a downregulated, differentially expressed protein in early versus advanced stages of nasopharyngeal carcinoma (NPC)." (PMID 40565234, 2025).
nephrotic syndrome (2 papers, 2015 to 2024). A collection of symptoms that include severe edema, proteinuria, and hypoalbuminemia; it is indicative of renal dysfunction. "With nephrotic syndrome as a condition associated with alternations in SHBG concentration." (PMID 26635963, 2015).
pancreatic cancer (2 papers, 2019 to 2021). "Interestingly, higher SHBG levels have been associated with a lower BMI and a decreased risk of T2D, but higher SHBG levels have also been found in advanced pancreatic cancer cases." (PMID 34329319, 2021). "The serum levels of SHBG were elevated in advanced pancreatic cancer patients, which may imply a worsened survival as compared to the controls." (PMID 31346328, 2019).
Primary hypogonadism (2 papers, 2018 to 2023). "Therefore, we hypothesize that serum SHBG is the key factor in reducing serum cFT levels, and obese rats may develop mild primary hypogonadism (reduced serum TT and cFT, increased SHBG)." (PMID 29769123, 2018). "Primary hypogonadism is essentially due to a rise in SHBG and to the absence of LH-related compensatory increase in T synthesis, likely resulting from a mitotane-induced direct damage to the Leydig cells." (PMID 38269251, 2023).
Sepsis (2 papers, 2016 to 2021). Sepsis is defined as life-threatening organ dysfunction caused by a dysregulated host response to infection. "Therefore, if sepsis causes relatively low albumin and high SHBG concentrations, septic patients could have high total but low bioavailable estradiol levels." (PMID 27765072, 2016). "Similar to CBG, SHBG is produced by the liver and affected by diseases; in people, SHBG is negatively correlated with sepsis severity." (PMID 33277956, 2021). "Sepsis patients had lower albumin concentrations and higher SHBG concentrations than control subjects." (PMID 27765072, 2016).
squamous cell carcinoma (2 papers, 2022 to 2024). A carcinoma arising from squamous epithelial cells. "Our study results suggest a bidirectional causal relationship between squamous cell carcinoma and SHBG." (PMID 39687887, 2024).
thyroid nodule (2 papers, 2023 to 2025). A small circumscribed mass in the THYROID GLAND that can be of neoplastic growth or non-neoplastic abnormality. "In contrast, a close and inverse relationship between thyroid nodules prevalence and serum sex hormone binding globulin (SHBG) levels was demonstrated in men, with a 1.91-fold lower risk in the lowest quartile of SHBG levels versus the highest quartile of SHGB levels." (PMID 37635968, 2023).
TSHomas (2 papers, 2022 to 2024). "Patients with TSHomas typically present with elevated SHBG, bs-ALP, carboxy-terminal cross-linked telopeptide of type I collagen (ICTP), and ferritin." (PMID 38642582, 2024).
Varicose veins (2 papers, 2022 to 2023). Enlarged and tortuous veins. "According to the results in the univariable MR analysis, serum SHBG levels seemed to be associated with lower extremity varicose veins." (PMID 38152135, 2023). "We found that increased serum SHBG levels were genetically associated with an increased risk of lower extremity varicose veins (OR=1.39; 95% CI: 1.13–1.70; P=1.58×10-3)." (PMID 38152135, 2023). "Gender-stratified MR revealed that higher serum SHBG levels were associated with lower extremity varicose veins in both sexes." (PMID 38152135, 2023). "We first explored the possible associations between serum SHBG and sex hormones levels and lower extremity varicose veins using univariable MR analysis." (PMID 38152135, 2023). "In the MVMR analysis, higher serum SHBG levels remained causally related to a higher risk of lower extremity varicose veins." (PMID 38152135, 2023). "Second, while the causal relationship between serum SHBG levels and lower extremity varicose veins was revealed, the underlying mechanism is still equivocal and further research is needed." (PMID 38152135, 2023). "Serum SHBG levels are positively related to lower extremity varicose veins risk in both sexes, especially in females." (PMID 38152135, 2023). "Genetically predicted higher serum SHBG levels significantly increased the risk of lower extremity varicose veins in the univariable MR analysis (OR=1.39; 95% CI: 1.13–1.70; P=1.58×10-3)." (PMID 38152135, 2023). "We find that serum SHBG levels are positively related with lower extremity varicose veins risk in both sexes, especially in females." (PMID 38152135, 2023). "Lastly, we performed a gender-stratified MR analysis to investigate if there was a gender difference in the causal effect between serum SHBG levels and lower extremity varicose veins risk." (PMID 38152135, 2023). "Our findings showed a positive association of serum SHBG levels with the risk of lower extremity varicose veins in both sexes, especially in females, and extended the limited evidence concerning the role of serum SHBG levels in lower extremity varicose veins." (PMID 38152135, 2023). "The OR of SHBG levels was 1.50 (95% CI:1.13-1.99; P=5.61×10-3), indicating that there was an independent causal effect of SHBG levels on lower extremity varicose veins." (PMID 38152135, 2023). "Specifically, for 1-standard deviation increase in serum SHBG levels, the risk of lower extremity varicose veins increases 51% and 26% in females and males, respectively." (PMID 38152135, 2023). "Analysis showed that serum SHBG levels were associated with lower extremity varicose veins risk in both sexes." (PMID 38152135, 2023). "First, a univariable MR was performed to identify the causality from SHBG and sex hormone levels to lower extremity varicose veins with several sensitivity analyses being performed." (PMID 38152135, 2023). "In summary, this is the first MR study to reveal the associations between serum SHBG levels and the risk of lower extremity varicose veins at gender-stratified level." (PMID 38152135, 2023). "Two adverse outcomes, varicose veins and fracture, were identified to be associated with higher levels of genetically predicted SHBG mainly in females." (PMID 35218343, 2022). "As a result, it remained unclear whether there existing associations between the serum levels of SHBG and sex hormones and the risk of lower extremity varicose veins." (PMID 38152135, 2023). "Notably, women’s risk for varicose veins increased to a greater extent than men’s when faced with increased serum SHBG levels." (PMID 38152135, 2023). "Notably, although serum SHBG levels were associated with lower extremity varicose veins risk in both sexes, the association seemed to be stronger in females." (PMID 38152135, 2023). "However, the OR of serum SHBG levels on lower extremity varicose veins risk in females (OR=1.51; 95% CI: 1.23–1.87; P=1.00×10-4) was greater than in males (OR=1.26; 95% CI: 1.04–1.54; P=1.86×10-2)." (PMID 38152135, 2023).
Varicose veins (continued). "In this study, we conducted an MR analysis using large-scale genome-wide association study (GWAS) summary data to investigate the relationships between the serum levels of SHBG, testosterone, and estradiol (as exposures) and the risk of lower extremity varicose veins (as outcome)." (PMID 38152135, 2023). "Moreover, less attention has been paid to the association between serum SHBG and lower extremity varicose veins." (PMID 38152135, 2023). "Results showed that the causal effect of serum SHBG levels on lower extremity varicose veins risk was retained (OR=1.50; 95% CI:1.13-1.99; P=5.61×10-3), indicating that serum SHBG levels had an independent causal effect on lower extremity varicose veins risk." (PMID 38152135, 2023). "Therefore, it can be further inferred that the stronger association between SHBG and lower extremity varicose veins in females may partly explain the fact that veins are more prevalent among females." (PMID 38152135, 2023). "Besides, serum sex hormone-binding globulin (SHBG) has been rarely studied in lower extremity varicose veins." (PMID 38152135, 2023). "By combining evidences from the univariable MR analysis, MVMR analysis and the gender-stratified MR analysis, we believe that, compared to individuals with normal SHBG levels, people with higher serum SHBG levels are more likely to suffer from lower extremity varicose veins." (PMID 38152135, 2023). "Besides, it has been widely proved that the SHBG level of middle-aged and elderly women is higher than that of men of the same age, and the data for SHBG and lower extremity varicose veins that we included were also from participants in this age group." (PMID 38152135, 2023).
abortion (1 paper, 2016). the ending of pregnancy by removing a fetus or embryo before it can survive outside the uterus. "The SHBG:g.27956790C>T mutation appeared unlikely to be responsible for the present case of abortion and, in addition, we observed this mutation in a homozygous state in a living animal." (PMID 27472836, 2016).
adenoma (1 paper, 2021). A neoplasm arising from the epithelium. "We observed an inverse association of SHBG with risk of overall conventional adenomas and advanced adenomas, as well as a suggestive positive association for free estradiol and free testosterone." (PMID 33504335, 2021). "SHBG was inversely associated with risk of advanced conventional adenomas (P for trend < 0.0001), with the OR comparing extreme quartiles of 0.40 (95% CI 0.24–0.67)." (PMID 33504335, 2021). "In this retrospective analysis of 5404 postmenopausal women in the NHS cohorts, we found that higher concentrations of SHBG were associated with lower risk of conventional adenomas, particularly advanced adenomas." (PMID 33504335, 2021). "Higher concentrations of SHBG were associated with lower risk of conventional adenomas (P for trend < 0.0001), with the multivariable OR of 0.47 (95% CI 0.35–0.64) comparing the highest to the lowest quartile." (PMID 33504335, 2021). "In the stratified analysis by the time interval since blood draw, the inverse association between SHBG and adenoma was statistically significant in both subgroups (< and ≥ 11 years)." (PMID 33504335, 2021). "Higher concentrations of SHBG were associated with lower risk of conventional adenomas, particularly advanced adenomas (multivariable OR comparing the highest to the lowest quartile, 0.40, 95% CI 0.24–0.67, P for trend < 0.0001)." (PMID 33504335, 2021). "Furthermore, we found that higher SHBG levels were associated with lower risk of conventional adenomas, particularly advanced lesions." (PMID 33504335, 2021). "In addition, a suggestive association was found for SHBG with lower risk of large serrated polyps and free estradiol and free testosterone with higher risk of conventional adenomas." (PMID 33504335, 2021).
autism spectrum disorder (1 paper, 2021). A spectrum of developmental disorders that includes autism, and Asperger syndrome. "To test the generalization of the hypothesis that emerged from our previous analyses, that is, that higher testosterone and lower SHBG levels might lead to deficits in social behavior, we used SPARK, a large, US-based nationwide genetic study of autism spectrum disorders." (PMID 34108004, 2021).
Autoimmunity (1 paper, 2025). The occurrence of an immune reaction against the organism's own cells or tissues. "In men, the presence of anti-thyroid peroxidase antibodies (anti-TPO) leads to lower SHBG concentration, nevertheless, this correlation is not an independent predictor of autoimmunity." (PMID 40427034, 2025).
benign neoplasm of uterus (1 paper, 2022). "In addition, our analysis added information on the protective effect of high SHBG on benign neoplasm of uterus." (PMID 35218343, 2022).
blood pressure (1 paper, 2013). "In conclusion, these results show a strong association between SHBG and blood pressure independent of major determinants of high blood pressure." (PMID 23594436, 2013).
breast tumors (1 paper, 2022). "Insulin and insulin-like growth factor-1 (IGF-1) are the most important negative regulators of the sex hormone-binding globulin (SHBG) synthesis pathway in vitro and may lead to the development of breast tumors in a variety of ways." (PMID 35464024, 2022).